MEN1 (menin 1)
Diseases named in the same sentence as MEN1 in open-access papers (continued):
Sharing a sentence is not in itself a finding about the gene and the disease.
prolactinoma (6 papers, 2019 to 2024). "Collectively, these findings suggest that MEN1-associated PRLomas, especially macro-PRLomas, might exhibit decreased responsiveness to DA therapy." (PMID 39439563, 2024). "In conclusion, our study involving 84 MEN1-related PAs with extensive follow-up revealed that microadenomas associated with MEN1 generally have a low risk of progressing to macroadenomas, with micro-PRLomas exhibiting a higher risk over a long time." (PMID 39439563, 2024). "This underscores the importance of comprehensive studies that include MEN1 patients and control groups with both micro- and macro-PRLomas to definitively understand the efficacy of DA therapy in these cases." (PMID 39439563, 2024). "A cohort study on PA in MEN1 patients showed that prolactinomas and NFPAs accounted for 45.5% and 36.1%, respectively." (PMID 37324275, 2023). "MEN1 mutation related prolactinoma respond well to dopamine agonists while AIP mutation associated somatotroph and lactotroph adenoma are frequently resistant to medical treatment." (PMID 31920960, 2019). "Historically, prolactinomas (PRLomas) were considered the most common type of PAs in MEN1 patients and were thought to have similar behavior and treatment response as PAs that develop in non-MEN1 individuals." (PMID 39439563, 2024). "A large childhood-onset prolactinoma can be the first manifestation of MEN1 or AIP-related disease." (PMID 33543431, 2021). "Prolactinomas are the most common pituitary adenoma subtype in MEN1, and the second most common in MEN4 and FIPA, both in AIP-positive (even as a homogenous prolactinoma family) and AIP-negative FIPA, but can occur in SDHx cases as well." (PMID 33543431, 2021). "However, lack of comprehensive genetic testing is the limitation of this study, as up to 2.6% of patients with prolactinoma without related MEN1 symptoms may experience mutations in the MEN1 gene." (PMID 32849307, 2020).
somatotropinoma (6 papers, 2014 to 2025). "Characteristics of somatotroph tumors in MEN1 mutations include local invasion, multiple hormone-producing potential, and often treatment-resistant macroadenomas." (PMID 36010855, 2022). "While somatic mutations of GNAS are the most prevalent cause of somatotroph tumors, germline mutations in various genes (AIP, PRKAR1A, GPR101, GNAS, MEN1, CDKN1B, SDHx, MAX) are also known as the cause of somatotroph tumors." (PMID 36010855, 2022).
thymic tumors (6 papers, 2018 to 2026). "The two-hit of MEN1 germline and somatic mutations occurred in the thymic tumor of the proband’s son." (PMID 41736142, 2026). "The goal of this study was to investigate the molecular aspects of MEN1-associated thymic tumors including LOH at the MEN1 locus and RNA-sequencing (RNA-Seq) to identify genes associated with tumor development and potential targeted therapy." (PMID 34515662, 2021). "A retrospective chart review of 294 patients with MEN1 germline mutations identified 14 patients (4.8%) with thymic tumors (12 thymic NETs and 2 thymomas)." (PMID 34515662, 2021). "It is noteworthy that the two NENs of different grade in this case may represent the ability of MEN1-associated thymic tumors to progress from intermediate- to high-grade, a phenomenon that has been postulated in the lung." (PMID 35696052, 2022). "The molecular insights gained from our study about thymic tumors combined with similar data from other MEN1-associated tumors may lead to better surveillance and treatment of these rare tumors." (PMID 34515662, 2021). "However, this hypothesis has seldom been reported in connection with MEN1-associated thymic tumors." (PMID 41736142, 2026). "Approximately 20–25% of t-NENs occur in patients with MEN1, and thymic tumors themselves account for a significant proportion (up to ~20%) of MEN1-related mortality." (PMID 41463183, 2025). "In conclusion, we show for the first time that, somatic LOH at the MEN1 locus is the mechanism for thymic tumor development in MEN1 patients." (PMID 34515662, 2021). "The 13 different heterozygous MEN1 germline mutations identified in the 14 cases with thymic tumors (patients 4 and 8 were from the same family) were scattered throughout the entire MEN1 coding region without specific clustering." (PMID 34515662, 2021). "Another limitation of our study is that we compared the transcriptome of thymic tumors to normal thymuses, given that no cell-of-origin has been shown for MEN1-associated thymic tumors." (PMID 34515662, 2021). "Additionally, thymic neuroendocrine tumors (th-NETs) are rarer than thymic tumors, representing approximately 2–5% of all thymic tumors, and only 25% of th-NETs are also diagnosed with MEN1." (PMID 32126984, 2020). "Whole transcriptome analysis of MEN1-associated thymic tumors has not been reported." (PMID 34515662, 2021). "Therefore, it is generally thought that thymic tumor development in MEN1 patients is dependent on other somatic molecular events rather than a second hit to the MEN1 gene, and its pathogenesis is largely unknown." (PMID 34515662, 2021). "LOH at the MEN1 locus was identified in 10 tumors including the 2 thymomas, demonstrating that somatic LOH at the MEN1 locus is also the mechanism for thymic tumor development." (PMID 34515662, 2021). "In patients with MEN4 the need for thoracic imaging, as performed in patients MEN1 for early diagnosis of bronchopulmonary NET and thymic tumors, might be waived." (PMID 30254610, 2018). "LOH at the MEN1 locus has not been demonstrated in thymic tumors." (PMID 34515662, 2021).
thyroid cancer (6 papers, 2015 to 2025). "The elevated thyroid cancer prevalence is attributable to detection bias, as MEN1 patients undergo frequent cervical imaging for parathyroid evaluation, leading to incidental identification of thyroid malignancies." (PMID 40607214, 2025).
colorectal cancer (5 papers, 2017 to 2023). A primary or metastatic malignant neoplasm that affects the colon or rectum. "While MEN1 was reported that it could be a novel driver causing the dysregulation of Wnt signaling pathway in colorectal cancer." (PMID 35154239, 2021). "MEN1 has previously been implicated in cancers of endocrine origin, but has not been identified as a tumor suppressor gene in colorectal cancer." (PMID 32384699, 2020). "WNT16 and MEN1 may be novel drivers of aberrant WNT signaling in colorectal cancer." (PMID 32384699, 2020).
duodenal gastrinomas (5 papers, 2017 to 2025). "MEN1-ZES is caused by one or multiple duodenal gastrinomas, which are malignant in a high proportion of 60–80%, and in 77.2% in our series." (PMID 35454834, 2022). "MEN1/ZES patients almost invariably have multiple duodenal gastrinomas which are microscopic to small (many <0.5 cm) and thus difficult to find at surgery and completely remove even with a duodenectomy." (PMID 41463062, 2025). "It is also reported that pancreatic gastrinoma is rare in MEN1, however is more aggressive than duodenal gastrinoma." (PMID 28270118, 2017).
hypercortisolism (5 papers, 2021 to 2025). "Other associated MEN1-derived clinical conditions, such as hypogonadism, growth hormone deficiency, hypercortisolism, and/or nutrient malabsorption caused by surgical resection of the proximal tract of the small intestine, may worsen bone loss in MEN1 patients with PHPT." (PMID 34440663, 2021). "Because of the potential clinical complexity in MEN1 and the fact that hypercortisolism can result from pituitary, adrenal, or other endocrine tumors, finding an etiology for MEN1-associated CS be challenging." (PMID 37409236, 2023). "In addition, other MEN1 manifestations, such as hypercortisolism and hyperprolactinemia, can reduce BMD." (PMID 39575107, 2024). "In a retrospective series of 19 MEN1 patients with CS evaluated at one institution, an etiology could not be found in five patients, and among these the hypercortisolism appeared to resolve spontaneously in three." (PMID 37409236, 2023). "It is therefore important to consider all etiologies for patients with MEN and CS, since hypercortisolism due to CD, adrenal etiologies, and the ectopic secretion of ACTH are well-documented in MEN1 just as in non-familial cases." (PMID 37409236, 2023).
hyperinsulinism (5 papers, 2014 to 2023). Abnormally high levels of insulin in the blood. "All 8 patients with MEN1-associated benign insulinoma in the present cohort were also surgically cured of their organic hyperinsulinism, which supports recommendations for a potentially parenchyma-sparing approach for this subgroup as well." (PMID 37386194, 2023). "The examinations of fasting serum insulin levels showed that the β-catenin deletion rescued the hyperinsulinemia in Men1-deficient mice." (PMID 25517963, 2014). "All MEN1 patients with organic hyperinsulinism in our collective were biochemically cured after surgery and none of these patients developed a relapse during long-term follow-up so far." (PMID 37386194, 2023). "In our previous report, a 23-year-old male MEN1 patient was hospitalized for hyperinsulinemia-induced morning hypoglycemic comas." (PMID 35954231, 2022).
hyperplasia (5 papers, 2011 to 2025). An abnormal increase in the number of cells in an organ or a tissue with consequent enlargement. "Mean age of tumour/hyperplasia diagnosis was 47.0 + 12.4 years (range 31–62 years), while mean age at MEN1 diagnosis was 39.1 + 12.2 years (range 21–73 years)." (PMID 30428914, 2018). "We report a 31 years-old female MEN1-patient, in whom hyperplasia of the parathyroid glands, prolactinoma, non functioning pancreatic endocrine carcinoma and functioning bilateral adrenal carcinomas were diagnosed." (PMID 21266030, 2011). "Although involvement of the adrenal gland has been reported in approximately 40% of MEN1 patients and has been found to represent bilateral hyperplasia, adenoma and in a few cases carcinoma, bilateral adrenal carcinoma has not been previously reported." (PMID 21266030, 2011). "The incidence of multiple adenomas or hyperplasia in patient with non-MEN1-related PHPT is as low as 7%, while that of involvement of two or more parathyroid glands by MEN1-related PHPT rises significantly to 56%." (PMID 37795364, 2023). "Heterozygous Men1(+/T) knockout mice do not develop bronchopulmonary neuroendocrine hyperplasia or neoplasia." (PMID 40277511, 2025).
lung adenocarcinoma (5 papers, 2022 to 2025). A carcinoma that arises from the lung and is characterized by the presence of malignant glandular epithelial cells. "Loss of Men1 significantly accelerated the progression of Kras-driven lung adenocarcinoma and enhanced the accumulation of CD44v isoforms." (PMID 41369362, 2025). "The results of our study show that MEN1 deficiency caused an obvious reduction in the epithelial markers and an elevation of the expression of mesenchymal markers, which was consistent with our recent reports in lung adenocarcinoma." (PMID 35968938, 2022). "In the Marburg cohort of 115 patients with MEN1, none had adenocarcinoma of the lung." (PMID 40277511, 2025).
Osteopenia (5 papers, 2018 to 2024). Osteopenia is a term to define bone density that is not normal but also not as low as osteoporosis. "In addition, four patients (two premenopausal females and two males) with a mean age 30.25 ± 4.2 years were also diagnosed with osteopenia during screening for BMD measurement at the time the diagnosis of MEN1-related PHPT was established in our institution." (PMID 35407574, 2022).
ovarian carcinoma (5 papers, 2018 to 2023). A malignant neoplasm originating from the surface ovarian epithelium. "In patients with ovarian cancer, the mRNA level of MEN1 and ATM1 was reduced by 31% (p > 0.05) and 25% (p > 0.05), respectively." (PMID 35807169, 2022). "In our study, we showed a decrease in the mRNA and protein level for MEN1 in patients with ovarian cancer compared with healthy controls." (PMID 35807169, 2022). "The analysis of the mRNA and protein levels of the ATM and MEN1 showed no change in the expression level in patients with ovarian cancer compared with the control group." (PMID 35807169, 2022). "So far, the analysis of MEN1 gene expression has not been analyzed in ovarian cancer, so it is difficult to relate our results to other studies." (PMID 35807169, 2022).
pancreatic NEC (5 papers, 2011 to 2024). "It is noteworthy that the molecular analysis also identified MEN1 and DAXX mutations in four and two pancreatic NEC-like G3NETs, respectively." (PMID 39382626, 2024). "Additionally, this study brings to light a novel presentation of ACTH-producing pancreatic neuroendocrine carcinoma within the MEN1 spectrum, expanding our understanding of the disease’s manifestations." (PMID 39104820, 2024). "The occurrence of ACTH-producing pancreatic neuroendocrine carcinoma is exceedingly rare in MEN1." (PMID 39104820, 2024).
thyroid (5 papers, 2019 to 2025). "The incidence of cancer was markedly higher in the clinically suspected MEN1 group, with increased rates of thyroid, pancreatic, and liver cancers)." (PMID 40607214, 2025). "Thus, thyroid lesions are not considered MEN1-associated lesions." (PMID 37867522, 2023).
urolithiasis (5 papers, 2019 to 2025). Stone(s) within the urinary tract. "MEN-1 associated PHPT often manifests with mild elevations of serum calcium and iPTH, although there is data that bone disease and urolithiasis in MEN1-related PHPT showed an early onset and higher severity compared to sporadic disease." (PMID 37465121, 2023). "Up to two-thirds of patients with MEN1 present complications of urolithiasis (renal/ureteric colic, urinary tract infection) as the first clinical manifestation of the syndrome, and, in half of cases, urolithiasis is reported as the only clinical manifestation." (PMID 39519139, 2024). "For patients with recurrent urinary stones, we recommend measuring blood calcium and PTH, and if there is an abnormality, screening other endocrine glands to exclude MEN1." (PMID 40421248, 2025). "For patients with recurrent urinary stones, we recommend measuring blood calcium and PTH, and if there are abnormalities, screening other endocrine glands to exclude the possibility of MEN1." (PMID 40421248, 2025). "In the present case, the patient had recurrent urinary stones for more than 10 years and had been treated with extracorporeal lithotripsy, but the attending physician had never considered the possibility of MEN1." (PMID 40421248, 2025).
acute leukemia (4 papers, 2022 to 2025). A clonal (malignant) hematopoietic disorder with an acute onset, affecting the bone marrow and the peripheral blood. "For instance, in acute leukemia, secondary mutations in the MEN1 gene can be detected when patients experience relapse." (PMID 41335282, 2025).
carcinoid tumours (4 papers, 2017 to 2024). "Radiological examinations such as MRI or CT are helpful to detect pituitary, pancreatic, adrenal or carcinoid tumours while DNA analysis helps ascertain germline mutations including MEN1, RET and CDKN1B." (PMID 31797261, 2020). "In patients with MEN1, carcinoid tumours often remain silent and devoid of clinical symptoms until reaching an advanced stage with malignant characteristics." (PMID 39258048, 2024).
Esophageal stricture (4 papers, 2017 to 2026). A pathological narrowing of the esophagus that is caused by the development of a ring of scar tissue that constricts the esophageal lumen. "In conclusion, MEN1-ZES can develop severe esophageal strictures, which can be treated by anti-acid therapy and repetitive endoscopic balloon dilation." (PMID 28270118, 2017). "Here, we reported a case of MEN1/ZES, who developed dysphagia due to reflux esophagitis with severe esophageal stricture." (PMID 28270118, 2017). "Patients with MEN1 and ZES may present with esophagitis, dysphagia, and heartburn, and are three times more likely to have esophageal strictures and duodenal ulcers." (PMID 37090344, 2023).
glioma (4 papers, 2012 to 2022). A benign or malignant brain and spinal cord tumor that arises from glial cells (astrocytes, oligodendrocytes, ependymal cells). "MEN1 expression was activated in 44.4% of adult gliomas and predicted poor prognosis of patients with glioma." (PMID 32373523, 2020). "Importantly, MEN1 inhibitors significantly decreased the proliferation of adult glioma cells." (PMID 32373523, 2020).
Glucose intolerance (4 papers, 2012 to 2024). Glucose intolerance (GI) can be defined as dysglycemia that comprises both prediabetes and diabetes. "Among the cardiovascular diseases, conditions at particular risk of complications include hyperparathyroidism and glucose intolerance/diabetes, these latter being reported to occur with a higher frequency in MEN1 patients." (PMID 33312161, 2020). "They described a family in which three persons had α-cell pancreatic tumors (i.e., glucagonomas) as part of MEN1, among which two had the classic glucagonoma syndrome with skin rash, glucose intolerance, and hypoaminoacidemia." (PMID 38294658, 2024). "In asymptomatic MEN1 patients, the presence of the tumor can be suspected upon pancreatic imaging in the presence of glucose intolerance and hyperglucagonemia." (PMID 33312161, 2020). "Clinicians should pay attention to the clinical features of MEN1 including glucose intolerance." (PMID 39726845, 2024).
Insulin resistance (4 papers, 2022 to 2025). Increased resistance towards insulin, that is, diminished effectiveness of insulin in reducing blood glucose levels. "Patients with MEN1 had a significantly higher prevalence of insulin resistance with an odds ratio of 5.58 (95% confidence interval [4.02, 7.74]." (PMID 41641294, 2025). "Multiple studies previously showed increased prevalence of insulin resistance and incidence of cardiovascular diseases, decreased life expectancy in patients with MEN1." (PMID 41641294, 2025). "Studies involving at least 5 patients with MEN1 and reporting on insulin resistance were included." (PMID 41641294, 2025). "This particularly high percentage of DM could be related to the increased insulin resistance, higher prevalence of impaired fasting glucose tolerance, and increased prevalence of DM often observed in MEN1 individuals than in controls." (PMID 37894286, 2023). "We have identified a higher prevalence of insulin resistance among individuals with MEN1 compared to controls, independent of age, sex, or body mass index." (PMID 41641294, 2025).
ovarian tumours (4 papers, 2020 to 2026). "In order to investigate menin role in OC development, we analysed RNA-seq data from ICGC and GTEx expression profiling datasets and found out that MEN1 expression level is increased in ovarian tumours in comparison to normal tissues." (PMID 36333801, 2022). "Ovarian tumours were detected from 12 months of age in 129S6/SvEv Men1+/- mice and from 17 months of age in C57BL/6 Men1+/- mice, which was not statistically significantly different." (PMID 32348957, 2020). "However, the occurrence of ovarian tumours was higher in 129S6/SvEv Men1+/- mice compared to that in the C57BL/6 Men1+/- mice (32.4% vs 10.8%, respectively, P < 0.005)." (PMID 32348957, 2020). "We also show that tumour development is not just accelerated in the C57BL/6 model, as we observed a significant increase in the occurrence of adrenal and ovarian tumours in the 129S6/SvEv, when compared to the C57BL/6 Men1+/- mice." (PMID 32348957, 2020).